MAPKAPK2 (MAPK activated protein kinase 2)
Diseases named in the same sentence as MAPKAPK2 in open-access papers (continued):
Sharing a sentence is not in itself a finding about the gene and the disease.
glioma (continued). "MAPKAPK2 expression in human glioma tissues was detected by immunohistochemistry and analyzed from the transcriptome sequencing data in TCGA and CGGA." (PMID 38322416, 2024). "We performed the single-cell sequencing analyses from TCGA to clarify the specific cell type of MAPKAPK2 expression due to the heterogeneity and the complex components of glioma." (PMID 38322416, 2024). "Further enrichment analyses including GO enrichment analysis, KEGG signaling pathway enrichment analysis, and GSEA signaling enrichment pathway analysis were conducted to manifest the related function and signaling pathways of MAPKAPK2 in glioma." (PMID 38322416, 2024). "Consistently, high levels of MAPKAPK2 also predicted poor prognosis of glioma patients in the DSS and PFI analyses from TCGA." (PMID 38322416, 2024). "Further analyses of MAPKAPK2 expression in glioma tissues from multiple datasets of TCGA and CGGA indicated that MAPKAPK2 levels were higher in high-grade glioma especially GBM." (PMID 38322416, 2024). "In order to further explore the clinical significance of MAPKAPK2 in glioma, we investigated the prognostic value of MAPKAPK2 in glioma by the informatic analyses from the datasets in TCGA and CGGA." (PMID 38322416, 2024). "To further confirm the expression and relationship of MAPKAPK2 levels with these clinical pathological characters, we performed IHC detection of MAPKAPK2 in 93 glioma tissues and 25 para-tumor tissues." (PMID 38322416, 2024). "Our results further suggested glioma relevant targets that are involved in AKT-mTOR signaling (MAPKAPK2 and YBX1)." (PMID 23358700, 2013). "In summary, aberrantly expressed MAPKAPK2 is positively correlated with poor prognosis of glioma." (PMID 38322416, 2024). "Here, we speculated that MAPKAPK2 may be involved in the chemotherapy or radiotherapy resistance in glioma and more evidence may be needed to demonstrate the potential role of MAPKAPK2." (PMID 38322416, 2024). "These analyses provide evidence that MAPKAPK2 may be enrolled in the proliferation, migration, DNA damage repair, and immune regulation of glioma." (PMID 38322416, 2024). "Correlation of MAPKAPK2 mRNA with clinical characters of glioma patients in TCGA dataset." (PMID 38322416, 2024). "MAPKAPK2 may be involved in cell proliferation, cell migration, DNA damage repair, and immune regulation in glioma." (PMID 38322416, 2024). "These analyses indicated that MAPKAPK2 correlated with immune cell infiltration and may participate in the immune regulation of the glioma microenvironment." (PMID 38322416, 2024). "MAPKAPK2 is correlated with immune cell infiltration in glioma tissue." (PMID 38322416, 2024). "Mechanistically, MAPKAPK2 may regulate inflammatory cytokine, chemokine and chemokine receptor, and immune regulation molecule expression to facilitate glioma progression." (PMID 38322416, 2024). "The role of MAPKAPK2 in inflammation and immune regulation in glioma tissue may supply a new angle of view to glioma therapy." (PMID 38322416, 2024). "Our findings provided evidence that MAPKAPK2 may be a valuable target for evaluating glioma prognosis and developing clinical therapy." (PMID 38322416, 2024). "We assess the prognostic value of MAPKAPK2 in glioma and the biological function in GBM cells." (PMID 38322416, 2024). "In view of the function of MAPKAPK2 in glioma progression and the relationship with immune cell infiltration, the role of MAPKAPK2 in the regulation of the immune microenvironment in glioma is still obscure and the mechanism of promoting glioma progression remains unknown." (PMID 38322416, 2024). "The clinical significance and molecular function of MAPKAPK2 in glioma remain unclear." (PMID 38322416, 2024). "We found that MAPKAPK2 expression was predominantly enriched in IDH wild-type (wt) and 1p/19q non-codeletion glioma of which molecular subtypes predict poor prognosis of glioma patients from multiple datasets of TCGA and CGGA." (PMID 38322416, 2024).
glioma (continued). "In glioma, SPARC promotes invasion via upregulation of the p38 MAPK/MAPKAPK2/HSP27 signaling pathway, and promotes tumor cell survival by upregulating pAKT." (PMID 22480225, 2012). "Enriched MAPKAPK2 expression in microglia/macrophages and glioma cells might facilitate the production of IL10 to promote glioma progression." (PMID 38322416, 2024). "MAPKAPK2 levels were high in gliomas of dead patients rather than live patients according to overall survival (OS), disease-specific survival (DSS), and progression-free interval (PFI)." (PMID 38322416, 2024). "Meanwhile, high levels of MAPKAPK2 were positively correlated with poor prognosis of glioma patients with IDH mutant (mut) and 1p/19q non-codeletion gliomas but not in IDH wt and 1p/19q codeletion gliomas." (PMID 38322416, 2024). "Therefore, MAPKAPK2 is a valuable marker for the prognosis evaluation of glioma including the IDH mutant and 1p/19q non-codeletion cohorts." (PMID 38322416, 2024). "In addition to these, MAPKAPK2 is positively correlated with IL6, IL6R, IL10, IL10RB, TGFβ1, etc., in the present study, which may facilitate the glioma progression." (PMID 38322416, 2024). "However, MAPKAPK2 is positively correlated with a series of immune regulators such as CD274, CD276, PDCD1, and CD70, which probably affect the tumor killing effect of the infiltrated immune cells in glioma tissue." (PMID 38322416, 2024). "The survival analyses of subgroups of glioma indicated that high levels of MAPKAPK2 predict poor prognosis in grade 2 and grade 3 but not grade 4, which might be mainly caused by the limited number of patients with short survival time and low survival rate enrolled in the grade 4 cohort." (PMID 38322416, 2024). "MAPKAPK2 is prevalent in IDH wt and 1p/19q non-codeletion glioma patients and is correlated with poor prognosis of glioma patients." (PMID 38322416, 2024). "Moreover, MAPKAPK2 was prevalent in isocitrate dehydrogenase (IDH) wild-type and 1p/19q non-codeletion glioma cohorts and predicted poor prognosis of glioma patients." (PMID 38322416, 2024). "MAPKAPK2 predicts poor prognosis of glioma patients in the 1p/19q non-codeletion cohort but not in the codeletion cohort, which suggests that MAPAPK2 may assist in the prognosis evaluation of the glioma patients with 1p/19q non-codeletion." (PMID 38322416, 2024).
gastric cancer (3 papers, 2020 to 2023). A primary or metastatic malignant neoplasm involving the stomach. "In addition, in AGS gastric cancer cell line, we observed the activation of mitogen-activated protein kinase-activated protein kinase 2 (MAPKAPK-2), which is believed to be a downstream substrate and a direct target of p38 MAPK." (PMID 37373017, 2023).
Alzheimer disease (2 papers, 2020 to 2021). A progressive, neurodegenerative disease characterized by loss of function and death of nerve cells in several areas of the brain leading to loss of cognitive function such as memory and language. "For instance, gene knockout of Mapkapk2 improves functional recovery of animals after spinal cord injury, prevents neuronal death induced by amyloid beta 1–42 in a model of Alzheimer's disease, and prevents neuronal death in the MPTP model of Parkinson's disease." (PMID 31770590, 2020).
cardiac hypertrophy (2 papers, 2021 to 2023). "MAPK-Activated Protein Kinase 2 (MK2) is at the middle of this EV-mediated process of dysfunctional mitochondria transfer to target cells; its silencing prevented the cargo export in charge of endothelial cells and the inflammatory-related contribution to cardiac hypertrophy." (PMID 37175888, 2023).
ischemia (2 papers, 2020). A hypoperfusion of the BLOOD through an organ or tissue caused by a PATHOLOGIC CONSTRICTION or obstruction of its BLOOD VESSELS, or an absence of BLOOD CIRCULATION. "Many of them have been previously correlated with response to ischemia (MAP 4, HPX, S100A proteins) as well as with angiogenic- and revascularization-related processes (LCN2, LRG1, CD44, MAPKAPK2)." (PMID 32143690, 2020).
rheumatoid arthritis (2 papers, 2016 to 2021). A chronic, systemic autoimmune disorder characterized by inflammation in the synovial membranes and articular surfaces. "MAPKAPK2 deficient animals display significant attenuation of TNF-α production in response to LPS, resistance to the development of rheumatoid arthritis (RA), and a reduction in atherosclerotic lesion formation." (PMID 34445361, 2021).
Sepsis (2 papers, 2022 to 2024). Sepsis is defined as life-threatening organ dysfunction caused by a dysregulated host response to infection. "Furthermore, a role in sepsis-induced brain neurodegeneration would also be related to a concomitant sepsis-mediated activation of the P38 signal, increasing MAPKAPK2 phosphorylation and downstreaming P38." (PMID 39768830, 2024).
astrocytoma (1 paper, 2024). "Correspondingly, MAPKAPK2 expression analyses in different histological types also showed that MAPKAPK2 levels were elevated in GBM compared with astrocytoma, oligoastrocytoma, and oligodendroglioma." (PMID 38322416, 2024).
cholesteatoma (1 paper, 2013). A pathologic process characterized by the proliferation of keratinizing squamous epithelium resulting in the accumulation of keratin and cells in the middle ear and/or mastoid. "It is therefore proposed that HSP27 is very likely phosphorylated in response to VEGF via the p38 MAPK/MAPKAPK2 pathway during the progression of cholesteatoma." (PMID 23852020, 2013). "The side-by-side comparison of Ras, Raf, ERK1/2, MEK1/2, p38MAPK and MAPKAPK2 for each individual patient showed that these proteins are increased in cholesteatoma in comparison with those in retroauricular skin." (PMID 23852020, 2013). "Thus, Ras, Raf, ERK1/2, MEK1/2, p38MAPK and MAPKAPK2 in the tissues of cholesteatoma and the retroauricular skin of six patients was analyzed by Western blot." (PMID 23852020, 2013).
colitis (1 paper, 2023). Inflammation of the colon. "Finally, MAPKAPK2 is involved in gut inflammatory pathways and regulation of TNF gene expression, and its inhibition results in an improvement in animal models of colitis." (PMID 36378498, 2023).
COVID-19 (1 paper, 2023). A disease caused by infection with severe acute respiratory syndrome coronavirus 2. "In the plasma of the COVID-19 patients studied, a large group of modified MDA proteins are kinases (MAP kinase-activated protein kinase 2 (MAPKAPK2, P49137), ribose-phosphate pyrophosphokinase 3 (PRPS1L1, P21108), and cAMP-dependent protein kinase (PKA, P22612))." (PMID 37762413, 2023).
fungal infection (1 paper, 2020). "However, although we have provided some insights about the functional role of the TNFSF4 and MAPKAPK2 polymorphisms in determining the risk of IA, we believe that additional studies are still warranted to identify the exact mechanisms by which these loci modulate the risk of fungal infection." (PMID 33374839, 2020).
Hepatic steatosis (1 paper, 2024). Steatosis is a term used to denote lipid accumulation within hepatocytes. "On the other hand, the miR8126-5p mimic inhibited the expression of the putative target gene MAPKAPK2 (−37.60% ± 2.51; p < 0.001) at the mRNA level in the in vitro model that mimicked hepatic steatosis." (PMID 38338999, 2024). "Intriguingly, both miR8126 isoforms downregulated QKI and MAPKAPK2 gene expression in the HepG2 model that mimicked hepatic steatosis, despite prediction algorithms reporting that miR8126-3p could target QKI and miR8126-5p could target MAPKAPK2, and not vice versa." (PMID 38338999, 2024).
hypercalcaemia (1 paper, 2025). "Moreover, we noted that hypercalcaemia was most common in the group of patients with variant MAPKAPK2 rs4073250 AG, and least common in patients with genotype AA (p = 0.039)." (PMID 40508046, 2025).
metastatic tumors (1 paper, 2021). "Importantly, some of these genes (THBS1, MAPKAPK2, CD9, TXNIP) were strongly associated with IL-6 signaling, indicating that IL-6 or its associated genes are coupled with metastatic tumors, in alignment with our previous findings." (PMID 34140316, 2021).
motor neuron disease (1 paper, 2025). "One study focusing on motor neuron disease showed a crucial role of SHSP1 (small heat shock protein 1), which is phosphorylated by MAPKAPK2." (PMID 40508046, 2025).
multiple myeloma (1 paper, 2025). "In the present study, we showed that SNPs located in genes encoding RIPK1, RIPK3 and MAPKAPK2 may be associated with the clinical parameters of multiple myeloma." (PMID 40508046, 2025). "We hypothesise that SNPs located in RIPK1, RIPK3 and MAPKAPK2 could be associated with multiple myeloma survival, treatment outcome and clinical parameters." (PMID 40508046, 2025). "The associations we observed between polymorphisms in RIPK1, RIPK3, and MAPKAPK2 genes and patient survival and treatment response reflect deeper biological relationships between genetic variants of necroptosis pathways and the pathophysiology of multiple myeloma." (PMID 40508046, 2025). "We analysed six single-nucleotide polymorphisms in a population of patients with multiple myeloma (n = 205) and healthy volunteers (n = 100): RIPK1 rs2272990, RIPK1 rs9391981, RIPK3 rs724165, RIPK3rs3212243, MAPKAPK2, rs45514798 and MAPKAPK2 rs4073250." (PMID 40508046, 2025).
neuroblastoma (1 paper, 2020). Neuroblastoma (NB) is the most common solid, extracranial childhood tumor. "Neurite outgrowth in response to 13-cisRA in MAPKAPK2 knockdown cells was also seen in the PD neuroblastoma cell line COG-N-443h." (PMID 32409685, 2020).
pancreatic neuroendocrine tumor (1 paper, 2024). Pancreatic endocrine tumor, also known as pancreatic neuroendocrine tumor (PNET), describes a group of endocrine tumors originating in the pancreas that are usually indolent and benign, but may have the potential to be malignant. "Macrophages with MAPKAPK2 depletion present increased cytotoxicity to pancreatic neuroendocrine tumors." (PMID 38322416, 2024). "MAPKAPK2 also mediates the macrophage function by cytokine production in pancreatic neuroendocrine tumors." (PMID 38322416, 2024).
parasitic infection (1 paper, 2020). "In addition, another study showed that miR-125a, which is involved in determining the commitment and immunosuppressive capacity of Treg cells, was highly expressed in a model of parasitic infection and that it mediated its action through the regulation of both TNFSF4 and MAPKAPK2 genes." (PMID 33374839, 2020).
polyneuropathy (1 paper, 2025). A disease or disorder affecting more than one nerve. "MAPKAPK2 rs45514798 AA was associated with polyneuropathy after thalidomide therapy." (PMID 40508046, 2025). "Polyneuropathy as an adverse effect of therapy with thalidomide was significantly more common in patients with genotype rs45514798 AA (MAPKAPK2) and least common in patients with genotype GG." (PMID 40508046, 2025). "Polyneuropathy as an adverse effect of thalidomide therapy was significantly more common among patients with MAPKAPK2 rs45514798 AA and less common in patients with genotype GG (p = 0.013)." (PMID 40508046, 2025).
prostate carcinoma (1 paper, 2022). A carcinoma that arises from epithelial cells of the prostate gland. "Previous study has implicated MAPKAPK2 as an oncogene involved in tumorigenesis in lung, colorectal, skin, bladder, and prostate cancers." (PMID 35328346, 2022).
Pruritus (1 paper, 2022). Pruritus is an itch or a sensation that makes a person want to scratch. "LCK, AMD1, and MAPKAPK2 might be possible oxymatrine targets in the treatment of pruritus." (PMID 36210824, 2022).
psoriasis (1 paper, 2024). An autoimmune condition characterized by red, well-delineated plaques with silvery scales that are usually on the extensor surfaces and scalp. "Moreover, recent findings indicate that MAPKAPK2 can function as a positive modulator in inflammation, which has been demonstrated in psoriasis and lipopolysaccharide-induced liver damage." (PMID 38250706, 2024).
uterine cancer (1 paper, 2025). Primary or metastatic malignant neoplasm involving the uterine corpus and/or the cervix.
vitamin D deficiency (1 paper, 2023). A nutritional condition produced by a deficiency of VITAMIN D in the diet, insufficient production of vitamin D in the skin, inadequate absorption of vitamin D from the diet, or abnormal conversion of vitamin D to its bioactive metabolites. "Higher MAPKAPK2 mRNA levels were observed in TGCT cell lines after vitamin D stimulation; thus, a potential low value of MAPKAPK2 due to vitamin D deficiency may enhance the activity of matrix metalloproteinase and its sequential invasion." (PMID 37114140, 2023).
vitiligo (1 paper, 2026). Generalized well circumscribed patches of leukoderma that are generally distributed over symmetric body locations and is due to autoimmune destruction of melanocytes. "Mitogen-activated protein kinase-activated protein kinase 2 (MAPKAPK2) is implicated in oxidative stress responses, although its role in vitiligo remains uncertain." (PMID 42089058, 2026).